SNN (stannin)
Description:
Plays a role in the toxic effects of organotins. Plays a role in endosomal maturation.
Tractability: Antibody: UniProt predicts a signal peptide or a membrane-spanning region.
Gene: Protein-coding gene on chromosome 16 (11,668,027 to 11,679,159, forward strand). Ensembl gene ENSG00000184602.
Subcellular location: Mitochondrion outer membrane
Subcellular location (Human Protein Atlas): Cytosol
Gene Ontology:
Molecular function: metal ion binding
Biological process: response to toxic substance
Cellular component: cytoplasm; membrane; mitochondrial outer membrane
Genetic constraint (gnomAD): Loss-of-function variants: 5 observed, 5.4 expected, observed/expected ratio (o/e) 0.93, 90% interval 0.48 to 1.75. That is too few expected variants to judge how well the gene tolerates losing a copy. Missense variants: 110 observed, 112.05 expected, observed/expected ratio (o/e) 0.98, 90% interval 0.84 to 1.15. Synonymous variants: 62 observed, 49.73 expected, observed/expected ratio (o/e) 1.25, 90% interval 1.01 to 1.54.
Homologues: Orthologues: chimpanzee SNN (100% identical), macaque SNN (100% identical), guinea pig SNN (99% identical), rabbit SNN (99% identical), mouse Snn (98% identical), pig SNN (98% identical), rat Snn (98% identical), tropical clawed frog snn (89% identical), zebrafish snn (88% identical), rat Snn (84% identical).
Diseases named in the same sentence as SNN in open-access papers:
SNN is named in the same sentence as 8 diseases in open-access papers, as found by Europe PMC text mining. Sharing a sentence is not in itself a finding about the gene and the disease. The quoted sentences say what the papers report.
ankylosing spondylitis (1 paper, 2023). An autoimmune chronic inflammatory disorder characterized by inflammation in the vertebral joints of the spine and sacroiliac joints. "SNN, a protein-coding gene playing a role in the toxic effects of organotin and endosomal maturation, has been proved to be linked to SHBG and a number of other autoimmune diseases including ankylosing spondylitis, psoriasis, ulcerative colitis, Crohn’s disease, and sclerosing cholangitis." (PMID 37644603, 2023).
gastric cancer (1 paper, 2009). A primary or metastatic malignant neoplasm involving the stomach. "The genes PLA2G4A, BMP5, MMP6, KNNMB4 and DYM were candidates for the GP202 gastric cancer cell line and the genes TXNL4B, FOXK1, PTPRJ, and SNN were candidates for the IPA220 gastric cancer cell line." (PMID 19563644, 2009).
cancer (1 paper, 2021). A tumor composed of atypical neoplastic, often pleomorphic cells that invade other tissues. "We also know that SNN is highly involved in MAPK signaling pathways and MAPK signaling pathway has shown to be important in some cancers." (PMID 33098307, 2021).
SNN also shares sentences with these, for which no sentence is quoted: autoimmune disease (1 paper); Crohn disease (1); psoriasis (1); sclerosing cholangitis (1); ulcerative colitis (1).